CXCR4 (C-X-C motif chemokine receptor 4)
Diseases named in the same sentence as CXCR4 in open-access papers (continued):
Sharing a sentence is not in itself a finding about the gene and the disease.
infection (635 papers, 2004 to 2026). The state of being infected such as from the introduction of a foreign agent such as serum, vaccine, antigenic substance or organism. "Our data reveal that both recombinant X4-gp120 and virus-like particles expressing physiological levels of X4 Env proteins (gp120 and gp41) promote CXCR4 clustering, a phenomenon linked to cell infection." (PMID 42118136, 2026). "This study investigated the effects of chronic oral administration of a CXCR4 antagonist on neutrophil abnormalities and infection susceptibility in a CXCR2 LOF mouse model." (PMID 41451234, 2025). "Our findings provide evidence that oral administration of a CXCR4 antagonist can effectively correct blood and BM neutrophil abnormalities and reduce infection susceptibility in a CXCR2 LOF mouse model." (PMID 41451234, 2025). "Holm and colleagues have demonstrated that the infection of primary T cell cultures with the CXCR4-tropic HIV-1 variant ELI6, induce activation of CD4+ and CD8+ T cells, which subsequently undergo apoptosis." (PMID 40709192, 2025). "To elucidate the molecular mechanisms underlying the up-regulation of CD18 and CXCR4, we employed various specific antibodies to screen for alterations in key molecular signaling pathway in neutrophils before and after infection." (PMID 39703777, 2024). "Cell tropism in HIV‐1 is influenced by the usage of co‐receptors, with CXCR4 primarily facilitating infection in CD4+ T cells, while CCR5 is mainly associated with macrophage infection." (PMID 39319247, 2024). "Usually, viruses using CCR5 as the coreceptor (i.e., R5 viruses) are predominant during the early stage of the infection, whereas viruses using CXCR4 (X4 viruses) are often associated with a late and rapid clinical progression." (PMID 37243169, 2023). "During subtype B infection, viral variants have acquired the ability to use CXCR4 instead of CCR5 in 40% to 50% of subjects and accelerate the rate of disease progression." (PMID 36211390, 2022). "Bystander death is favored when infection involves X4-tropic viruses, under such conditions is associated with higher levels of expression of CXCR4." (PMID 35784348, 2022). "A strong correlation was found between CXCR4 internalization defect and severity of blood leukocytopenias and infection susceptibility, and between AKT activation and immunoglobulin A level and CD4+ T-cell counts." (PMID 36089616, 2022). "Broadly consistent with this, 23% of study participants harbored CXCR4-using variants, though most would have likely already reached the chronic phase of infection at study enrolment, despite their ART-naive status." (PMID 36680168, 2022). "The WHIM (warts, hypogammaglobulinemia, infection, and myelokathexis) syndrome caused by gain-of-CXCR4-function mutation manifests by HPV-induced extensive cutaneous warts but also anogenital lesions that eventually progress to dysplasia." (PMID 35154113, 2022). "We have demonstrated a link between infection-associated upregulation of miR-206 and suppression of neutrophil recruitment to the site of pathogenic mycobacterial infection involving the Cxcl12/Cxcr4 signalling pathway." (PMID 33826679, 2021). "The parental TZM-TK-SR39 cells were susceptible to infection with both CXCR4 tropic HIV-Lai and CCR5 tropic virus YU2." (PMID 33516234, 2021). "We sequenced the V3 loop of env and found that virions in the plasma remained CCR5-tropic for both animals, excluding the possibility of infection by CXCR4-tropic SHIV variants." (PMID 34099693, 2021). "In monkey models of infection, CXCR4 usage is associated with rapid depletion of naive cells in the blood and secondary lymphoid organs (SLOs)." (PMID 33872329, 2021). "Surprisingly, we found that higher expression of CXCR4 at 1.5 months post-infection was associated with a lower decrease in MuV-specific T-cell frequencies in the blood." (PMID 34960178, 2021).
infection (continued). "Recent work has highlighted Cxcr4 as a mediator of host infection-associated angiogenesis, while this study further links the Cxcl12/Cxcr4 signalling axis to virulence-dependent neutrophil recruitment during mycobacterial infections." (PMID 33826679, 2021). "Sadly, CXCR4-tropic HIV-1 virus in vitro challenge resulted in an infection in the patient’s cells, indicating risk of infection and the need for continuous monitoring." (PMID 32082282, 2020). "CXCR-4 plays an important role in target-oriented migration of stem and immune cells towards the site of infection, while recent studies even propose an association with neuroinflammation." (PMID 32033172, 2020). "While for CCR5-tropic 81A the rate of apoptosis in MDM was comparable to uninfected MDM, the infection of CXCR4-tropic NL4.3 in MDM was associated with a rate of 14.3% of apoptotic cells at day 6 reaching a peak of 43.5% at day 10 post-infection." (PMID 31234437, 2019). "CCR5-tropic viruses represent the predominant viral population right after initial infection, but CXCR4 tropic viruses are associated with progressive CNS injury." (PMID 30314515, 2018). "Emergence of CXCR4-using virus is a complex process, with lineages arising independently during the course of infection and the development of clinically relevant variants depending on both viral and host factors." (PMID 30586365, 2018). "The observed enhancement of R5 HIV-1 entry by CXCL14 was dependent on CXCR4, as infection of CXCR4-deficient GHOST cells that were engineered to coexpress CD4 and CCR5 by R5 HIV-1 was not affected by CXCL14." (PMID 28360196, 2017). "Most infecting HIV-1 variants utilise CCR5, while a switch to CXCR4-use occurs in the majority of infections." (PMID 29049306, 2017). "Subtype D infection, ISRs and CXCR4 tropism associated with CRF01_AE have all been associated with rapid disease progression, while subtype A has been associated with slower disease progression." (PMID 28489920, 2017). "Viruses using CCR5 are largely transmitted and endure throughout infection and those that use CXCR4 often emerge later on in the course of infection and have been associated with more rapid disease progression and CD4 cell decline." (PMID 28240046, 2017). "On the other hand, CCR5 (R5) tropic viruses are known to be associated with early stages of infection, whereas CXCR4 (X4) HIV-1 tropic strains prevail in advanced infection." (PMID 27356504, 2016). "Rare individuals homozygous for a naturally-occurring 32 base pair deletion in the CCR5 gene (CCR5∆32/∆32) are resistant to infection by CCR5-using (“R5”) HIV-1 strains but remain susceptible to less common CXCR4-using (“X4”) strains." (PMID 26631642, 2015). "The chemokine receptors (CKRs), mainly CCR5 and CXCR4 function as major coreceptors in infections caused by human immunodeficiency virus (HIV) and simian immunodeficiency virus (SIV)." (PMID 24980635, 2014). "In general, R5 viruses are predominant in the early stage of infection, whereas CXCR4-using viruses (dual-tropic and X4 viruses) emerge at the late stage of infection and are associated with disease progression in half of HIV-1-infected individuals." (PMID 24586840, 2014). "In this study, we demonstrated that the infection of primary CD4+ T cells with either CXCR4-tropic HIV-1NL4-3 or CCR5-tropic HIV-1YU2 causes CD4+ T cell depletion by both necroptosis and apoptosis." (PMID 24714696, 2014). "The contribution of CXCR4-deficient cells to the IgDlo CD95hi GL7+ GC population within the medLN was determined at various time points after infection and compared to the concurrent naive follicular compartment." (PMID 24184055, 2013). "The expression of CXCR4 is also increased following an exposure to most PAMPs and this will result in a higher susceptibility of mDCs to productive infection with X4-using HIV-1 strains." (PMID 23844079, 2013).
infection (continued). "The dramatic and near complete loss of peripheral CD4 T cells is typical of infection of macaques with CXCR4-utilizing SHIV strains." (PMID 23460840, 2013). "CXCR4-using viral variants emerge during infection in at least half of patients infected with HIV-1 subtype B." (PMID 24098454, 2013). "In these subjects, the development of phenotypically-verified CXCR4-using variants that were capable of entering primary CD4+ T-cells via CXCR4 was exceedingly rare, with such variants detected at advanced infection in only one subject." (PMID 23824043, 2013). "This phenomenon is most likely associated with an enhanced permissiveness of DCs to productive infection with X4 virus, which is linked to increased surface expression of CXCR4 and the acquisition of a maturation profile by DCs." (PMID 23844079, 2013). "In contrast, CD4+ naïve T cells (Tn) are more susceptible to trans infection with X4 virus in relation to expression of CXCR4." (PMID 24278768, 2013). "In a study of 539 recently diagnosed anti-retroviral naïve HIV-1 infected individuals in Belgium, CRF01_AE infection was associated with significantly increased CXCR4-use compared to subtype B-infection." (PMID 23421710, 2013). "Univariate analyses revealed three factors associated with infection by CXCR4-using viruses: the current CD4-cell count, the nadir CD4-cell count and current treatment with protease inhibitors." (PMID 23226258, 2012). "Our findings suggest that CB2R activation in CD4+ T cells can inhibit actin reorganization and impair productive infection following cell-free or cell-associated viral acquisition of CXCR4-tropic HIV-1 in resting cells." (PMID 22448282, 2012). "HIV-1 binds to chemokine receptors such as CCR5 and CXCR4 using SU, and can be inhibited from in vivo infection by mutation of the chemokine receptors or by incubation with chemokines, such as RANTES." (PMID 21281498, 2011). "In many patients, a typical pattern of viral evolution has been documented during the course of the infection with the emergence, usually in concomitance with the earliest signs of disease progression, of CXCR4-using variants." (PMID 21284904, 2011). "In subtype B infected subjects, baseline infection with a CXCR4-using virus is strongly associated with a greater decrease in CD4+ T cell count over time and a greater risk of disease progression." (PMID 21969855, 2011). "CXCR4-tropic SHIV89.6P infection causes an accelerated disease progress with rapid systemic loss of all CD4+ T cell phenotypes compared to CCR5-tropic SIV and HIV." (PMID 21359149, 2011). "A growing body of work has also implicated CXCR4 and various chemokines in regulating infection of resting CD4+ T cells, an important latent reservoir of HIV in infected individuals." (PMID 21949786, 2011). "By contrast, differentiating ES and MEF derived from 5T4 knockout (KO) mice show only intracellular CXCR4 expression but infection with adenovirus encoding mouse 5T4 restores CXCL12 chemotaxis and surface co-localization with 5T4 molecules." (PMID 20376365, 2010). "Typically, in the early phase of infection the HIV-1 has a tropism for CCR5 (R5 variants), in the late phase of the infection viruses (X4 variants) that preferentially use CXCR4 emerge." (PMID 20676362, 2010). "Dual-tropic, R5X4 viruses, or the rarer CXCR4-dependent viruses, are observed in late phases of the infection, and are usually associated with a faster progression to AIDS and to a marked decline of immune response." (PMID 21994649, 2010). "CCR5 is used almost exclusively for entry in early infection, but CXCR4-using viruses associated with greater morbidity and mortality emerge in approximately 50% of patients over the course of infection." (PMID 19479085, 2009). "R5 strains, which use CCR5 for entry, are responsible for the primary infection while X4 strains, which use CXCR4, emerge later in the course of infection and are associated with a severe depletion of CD4 T cells." (PMID 19492063, 2009).
infection (continued). "We further confirmed by siRNA knockdowns that the RHGP-identified cellular pathways are responsible for resistance to infection by either CXCR4 or CCR5 tropic HIV-1 variants." (PMID 19788744, 2009). "Other tropism variants including CXCR4-tropic variants (X4 virus) can grow at early stage of infection by needle stick injuries, but are replaced with the R5 viruses after seroconversion." (PMID 18787705, 2008). "There is a risk that pharmacologic inhibition of CXCR4 could disrupt immune homeostasis and mobilise hematopoietic stem cells (HSCs) from the bone marrow niche with a subsequent increase in the risk of infection or ectopic off-target organ effects." (PMID 41002447, 2025). "However, CCR5 is the principal co-receptor for the HIV infection of immune cells, since viral R5 strains are mostly responsible for the initial infection, whereas CXCR4-tropic strains only occasionally cause the initial infection." (PMID 41226631, 2025). "The observed binding disparity is consistent with the hypothesis that an imbalance in available natural ligands could contribute to selective pressures influencing coreceptor switching and the emergence of CXCR4-tropic variants in later stages of infection." (PMID 41303692, 2025). "In addition to the truncated CXCR4-318 variant, other CXCR4 variants also were capable of mediating infection, including WT CXCR4." (PMID 40284914, 2025). "While CCR5-using viruses are preferentially transmitted and typically predominate during early infection, available data suggest that 6–18% of individuals in early infection may harbor CXCR4-using variants." (PMID 36680168, 2022). "Thus, the high expression of CXCR3 and low levels of CXCR4 at 1.5 months post-infection associate with the decrease in T-cell frequencies, which implies migration to the inflammation site and bone marrow at 1.5 month." (PMID 34960178, 2021). "However, as expected, the H7 clone resisted infection with CCR5 tropic HIV YU-2 while still retaining susceptibly to CXCR4 tropic Lai." (PMID 33516234, 2021). "Binding of gp120 to CCR5 and CXCR4 is also linked to alterations in the cytoskeleton, which may be important in both pre-and post-entry stages of infection." (PMID 34429135, 2021). "As the CXCL12/CXCR4 chemotactic axis is important in many parts of the immune system, it may contribute to the greater susceptibility to infection observed in HHT." (PMID 34906163, 2021). "We show that host miR-206 is increased by pathogenic M. marinum to impede the host Cxcl12/Cxcr4 signalling axis, thereby reducing protective early neutrophil recruitment to the site of infection, aiding the creation of a permissive niche for mycobacterial infection." (PMID 33826679, 2021). "Hence, both CCR5- and CXCR4-tropic HIV-1 strains can cause CD4+ T cell depletion following infection via mucosal routes in a humanized mouse model." (PMID 30761146, 2019). "Indeed, human eosinophils express CD4 and CXCR4 and are susceptible to infection by CXCR4-tropic HIV-1, according to evidence in vitro." (PMID 29619379, 2018). "The evolution of CXCR4-using virus has been associated previously with increased disease progression when it occurred in untreated or sub-optimally treated individuals during the natural course of infection." (PMID 30586365, 2018). "In addition, our group confirmed significant suppression of HIV-1NL4-3 infection in cells by the expression of CXCR4 P191A mutation." (PMID 29872154, 2018). "Interestingly, when comparing the in vitro susceptibility to infection, Tregs were reported to be more susceptible to infection by CXCR4-tropic strains, while TEM were more susceptible to CCR5-tropic strains." (PMID 29706961, 2018). "The higher disorder tendency of the X4 virus V3 loop suggests it may be ‘stickier’ and able to use CXCR4 coreceptor more efficiently and therefore cause further infection of immune cells that express CXCR4." (PMID 29049306, 2017).
infection (continued). "For example, a highly pathogenic SHIV strain, SHIV-KS661, which has the env gene of HIV-1 89.6 and predominantly uses CXCR4 as the secondary receptor for infection, causes an infection that systemically depletes the CD4+ T-cells of rhesus macaques within 4 weeks following infection." (PMID 28431573, 2017). "To identify host cell factors involved in HIV-1 replication in human cells, we employed a genome-wide RNAi screen in the MT4C5 lymphoid cell line, a derivative of MT4 cells expressing CCR5 and susceptible to infection with CXCR4-tropic and CCR5-tropic HIV-1 strains." (PMID 28683086, 2017). "On the other hand, they strongly suggest that the mechanisms underlying the enhanced resistance of the Cxcr4+/1013 mice to infection are acting before larvae reach the bloodstream, and more generally bring evidence in support of the skin’s major role in the host defense against filariae." (PMID 27111140, 2016). "The resistant phenotype displayed by Cxcr4+/1013 mice might underlie, either that neutrophils must be in elevated numbers at the point of infection, and/or that mutant mice neutrophils have a heightened activation state or modified functions." (PMID 27111140, 2016). "We previously showed that the immune response is initiated by BM cells early after i.n. infection of mice with a fully virulent Y. pestis strain, causing rapid modulation of the BM CXCR4-SDF-1 axis and prompt mobilization of neutrophils into the circulation within 12–24 hpi." (PMID 25974210, 2015). "HLACs were pretreated with IL-21 and infected with replication competent CCR5-tropic (R5-HIV–green fluorescent protein (GFP)) or CXCR4-tropic (X4-HIV–GFP) HIV-1NL4-3-encoding green fluorescent protein (GFP) to allow for direct quantification of infection by flow cytometry." (PMID 26108174, 2015). "C8166 cells express CD4 and CXCR4 and are therefore susceptible to infection by NL4.3, IIIB and HE." (PMID 25499264, 2014). "In the majority of patients, viral variants using CCR5 as coreceptor (R5) remain present in the viral quasispecies and coexist with viral variants using CXCR4 (X4) and variants capable of using both CCR5 and CXCR4 (R5X4) during the remaining course of infection." (PMID 24098454, 2013). "Indeed, effector Treg were more susceptible than naïve Treg to in vitro HIV infection by CCR5-tropic HIV-1 BaL while naïve and effector Treg were similarly susceptible to CXCR4-tropic HIV-1 IIIB in vitro infection." (PMID 23908654, 2013). "The choice of coreceptor used by the virus is intimately linked to disease acquisition and pathogenesis as the majority of transmitted viruses use CCR5 to enter cells, while the appearance of viruses capable of using CXCR4 during infection is associated with a more rapid progression to AIDS." (PMID 22470838, 2012). "In addition, the binding between BSSL and CXCR4 should be further characterized including the effect of such binding on infection with CXCR4-using variants, CXCR4 signaling and CD4+ T-lymphocyte proliferation and migration." (PMID 22412885, 2012). "When present, these variants might contribute to the infection of follicular helper T-cells expressing CXCR4 and, hence, to their apoptosis." (PMID 22632376, 2012). "One of the highly pathogenic SHIV strains, SHIV-KS661, which has the env gene of HIV-1 89.6 and predominantly uses CXCR4 as the secondary receptor for its infection, causes an infection that systemically depletes the CD4+ T cells of rhesus macaques within 4 weeks after infection." (PMID 22364292, 2012). "In such a pathogenic scenario, CXCR4-tropic SHIVs would predominantly replicate in lymphoid tissues resulting in a very active acute infection followed by the control of viral replication during the chronic stage of infection." (PMID 21829366, 2011). "A recent study in a small number of HIV-1 individuals in whom low-level predicted CXCR4-using variants were detected early in infection showed that these variants could either persist or disappear over time." (PMID 21731496, 2011).